CXCL10 (C-X-C motif chemokine ligand 10)
Diseases named in the same sentence as CXCL10 in open-access papers (continued):
Sharing a sentence is not in itself a finding about the gene and the disease.
tumor (continued). "This set includes tumor expression of c-Met and serum levels of HGF, IL-6, IL-8, CXCL9, CXCL10 and CXCL11." (PMID 34200459, 2021). "The CXCL9 or CXCL10/CXCR3 axis regulates immune cell migration, differentiation, and activation, leading to tumor suppression, and a better understanding of potential mechanisms is necessary to develop effective cancer control." (PMID 34386037, 2021). "DCs also play an important role at the tumor site where, through the secretion of CXCL9 and CXCL10, cDC1s contribute to the recruitment and restimulation of T cells." (PMID 34062821, 2021). "CXCL10 is a chemokine that is involved in attracting CD4 and CD8 cells to the tumor microenvironment in a variety of tumors." (PMID 34447697, 2021). "Activated eosinophils can secrete chemokines CXCL9, CXCL10, CCL17, and recruit CD4+T and CD8+T cells into the tumour microenvironment." (PMID 35003085, 2021). "We found that the protein expression CXCL9 (p = 0.012), CXCL10 (p = 0.003), CXCL11 (p = 0.011), CXCL13 (p = 0.004) were higher in tumor tissues than that in adjacent tissues." (PMID 34321012, 2021). "In our study, tumor growth curves of xenografts were analyzed to confirm that in the early stages of tumorigenesis, BMPER was highly expressed, while CXCL10, HOXA9, and CD34 were lowly expressed." (PMID 32432046, 2020). "IFNα was also induced along with the inflammatory chemokines CXCL10, and CCL5, and their expression mirrored the kinetics of viral replication in the tumor in vivo and in vitro." (PMID 32581235, 2020). "Results suggested that the CXCL10 was significantly upregulated in DLBCL and showed tumor specificity to some extent." (PMID 33240622, 2020). "Among these chemokines and cytokines, we selected CXCL8, CCL2, CXCL10, and CCL20 for further study because of their critical role in cell infiltration into the tumor microenvironment." (PMID 32971847, 2020). "CXCL9, CXCL10, and CXCL11 in TME were primarily secreted by tumor cells, monocytes, fibroblasts, and endothelial cells in response to IFN-γ." (PMID 32685487, 2020). "In supernatants from tumour cell killing assays, we found a similar immune mediator profile (TNFα, MCP-1, IL-10, CXCL-10, IL-1β, IL-6, and IL-23) to that previously detected with IgE cross-linking on the surface of monocytes." (PMID 33203088, 2020). "We found that these receptors are highly correlated to the innate and adaptive immunity-related cells, as well as IL-10, IL-6, CXCL10, CCL2-CCL5, TGFB1 in KIRC tumors, whereas in KIPRP tumor tissues IL8, IL1A, and TNF were highly correlated." (PMID 33330620, 2020). "Macrophage treatment with these nanocomplexes did not reduce their viability and efficiently stimulated the secretion of the T-cell recruiter chemokines CXCL10 and CCL5, of great importance for an effective anti-tumor immune response." (PMID 32733469, 2020). "Their migration to inflamed tissues including tumor sites involves a series of chemokine receptors such as CCL3-5/CCR5, CXCL10/CXCR3, and CX3CL1/CX3CR1." (PMID 31991604, 2020). "It has been recently shown that innate immune sensing of tumors occurs through DC activation and regulation of tumor lymphocyte infiltration via production of CXCL9 and CXCL10." (PMID 32817121, 2020). "We found that in the tumor and the tumor microenvironment, CCL2 and CXCL10 localized in Nestin+, Iba-1+, CD16+ and CD163+ cells." (PMID 32943658, 2020). "Previous studies have correlated the accumulation of TILs in tumours with the expression of the chemokine receptor CXCR3 (receptor for CXCL9, CXCL10 and CXCL11)." (PMID 31803974, 2020). "The relationships between BMPER, CXCL10, and HOXA9 expression and the tumor blood vessels were determined in the early- (20, 30, and 40 days) and late-tumor growth stages (80 days)." (PMID 32432046, 2020). "Evidence from the engineered expression of CXCL10 in isogenic rectal CT26 cancer cells suggests that they provide a protective and anti-metastatic role, mediated mainly by adaptive immunity of tumor-infiltrating T cells." (PMID 33419310, 2020).
tumor (continued). "In the late-tumor growth stage, BMPER, CXCL10, and HOXA9 were all lowly expressed, while CD34 was highly expressed." (PMID 32432046, 2020). "Mature DCs can also secrete cytokines to foster T cell response and release chemokines such as CXCL9, CXCL10, CCL3, CCL4, and CCL17 to recruit T cells into the tumor bed." (PMID 33505304, 2020). "Among the top genes differentially expressed between sensitive and resistant cells, we identified a group of candidates related to tumor-microenvironment response (CCL5, CXCL10, IFIT3, IFI44, IFNL2)." (PMID 32365528, 2020). "During hetIL-15 therapy, we observed an upregulation of tumor IFN-γ, both mRNA and protein, together with enhanced expression of the IFN-inducible chemokines CXCL9 and CXCL10." (PMID 32461349, 2020). "IP-10 (CXCL10) is regarded as a “key driver chemokine” attracting CD8+ and CD4+ T cells to tumor sites and potentiating their function." (PMID 32411122, 2020). "Our previous study found that improved survival upon genetic loss of Erk5 in PtenΔ/Δ PCa model was related to increased levels of the T cell recruiting cytokines Ccl5 and Cxcl10 and enhanced T cell infiltration (predominantly CD4+) within the tumours." (PMID 31740786, 2020). "APOBEC3H was identified to demethylate and upregulate CXCL10 and improve CD8+ T cell tumor infiltration in the tumor microenvironment." (PMID 32775421, 2020). "Judicious regorafenib/anti-PD1 combination therapy can inhibit tumor growth and increase survival by normalizing tumor vasculature and increasing intratumoral CXCR3+CD8 T-cell infiltration through elevated CXCL10 expression in HCC cells." (PMID 33234602, 2020). "It has been reported that the tumor production of CXCL9 and CXCL10 was repressed by enhancement of H3K27me3 and DNMT1-mediated DNA methylation." (PMID 33031059, 2020). "CXCL9, CXCL10 and CXCL11, chemokine ligands for CXCR3, were expressed at high levels in the tumour locale." (PMID 32439888, 2020). "We suggest that CXCL10 and possibly CXCL9 differ from other chemokines by their ability to restrain tumor growth and enhance anti-tumor immunity." (PMID 32547545, 2020). "USP18 depletion has been demonstrated to result in the high production of T cell chemoattractant C-X-C motif chemokine ligand 10 (CXCL10), which recruits CD4+ T cells and leads to the creation of a tumor-suppressive microenvironment." (PMID 32957626, 2020). "Along with further tumor progression, BMPER expression was gradually reduced, while CXCL10 and HOXA9 expression was gradually elevated, which was spatially associated with CD34 expression." (PMID 32432046, 2020). "Our data provide direct evidence reinforcing the notion that EMT is associated with tumor immune inhibition, whereby Snail could serves as a transcription factor of DPP4, which induces local immunosuppression by negatively regulating lymphocyte trafficking via cleavage of the chemokine CXCL10." (PMID 32430013, 2020). "Analyses from adjacent normal and GC samples confirmed that immune-related status was passive in the tumor microenvironment compared to normal tissues, as reflected by scarce expression of chemokines CXCL9, CXCL10, and CCL2, leading to IFN-γ restriction." (PMID 31903134, 2020). "For example, CD8+ T cells can induce tumor cell dormancy via the production of IFN-γ, and CD4+ T cells produce CXCL9 and CXCL10, avoiding micro angiogenesis and promoting hypoxic-induced dormancy." (PMID 32028565, 2020). "In vitro inhibition of BMPER, CXCL10, or HOXA9 expression reduced the ability of tumor cells to form tube like structure." (PMID 32432046, 2020). "CXCL-10, a chemoattractant, which is upregulated during IRI, promotes macrophage infiltration in the liver and macrophage activation in tumours with more tumour invasion and infiltration to blood vessels after transplantation." (PMID 32806712, 2020). "CXCL10 protein levels were equivalent between tumors implanted in ALK5ΔCD8 and WT animals at day 14 in the MC38 tumor model." (PMID 32273499, 2020).
tumor (continued). "A2BR antagonist, ATL801, reduces metastases by more than 80% in mice, which is due to increased IFN-γ, IFN-inducible chemokine CXCL10, a ligand for CXCR3, and tumor-infiltrating CXCR3+ T cells." (PMID 32351498, 2020). "Therefore, CXCL10 might be the key effector gene and have an effect on tumor immunity in HR DLBCL." (PMID 33240622, 2020). "In another aspect, for the γδ T cells, tumor-intrinsic mTOR inhibition promotes the epidermal recruitment of CXCL10-mediated CXCR3+ γδ T-cell and shows anti-tumor effect." (PMID 32483450, 2020). "CXCL10, which plays essential roles in helping CD8+ T cell trafficking and infiltration into the tumor microenvironment, was substantially hypomethylated in the promoter region and upregulated in the APOBEC3H-high group." (PMID 32775421, 2020). "To address the mechanisms underlying the antitumor effects of celecoxib, we focused on the tumor microenvironment and examined the levels of chemokines CCL2 and CXCL10 and their receptors, CCR2 and CXCR3, respectively." (PMID 32943658, 2020). "On day 20 of tumor growth, BMPER was highly expressed, while CXCL10, HOXA9 and the tumor blood vessel marker CD34 were lowly expressed." (PMID 32432046, 2020). "The CXCR3 ligands CXCL9, CXCL10 and CXCL11 were all elevated in the tumour, suggesting that the CXCL9/CXCL10/CXCL11–CXCR3 axis is involved in both CD4+ and CD8+ T cell infiltration into the tumour." (PMID 32439888, 2020). "Chemokines such as CXCL9 and CXCL10 can orchestrate the migration of effector CXCR3+ immune cells such as Th1 cells into the tumor sites, subsequently shaping both the tumor immunity and therapeutic responses." (PMID 31991604, 2020). "After contact with each other, T cells and tumor cells secrete CXCL9 and CXCL10, induced by INF-γ, with a positive feedback mechanism to increase the infiltration of immune cells (CD8+ T cells, NK cells, and macrophages) within the tumor." (PMID 33330629, 2020). "Meanwhile, CXCL9, CXCL10 and CXCL11, chemokine ligands for CXCR3, were expressed at high levels in the tumours, thus attracting CXCR3+CD8+ T cells." (PMID 32439888, 2020). "Of these, BMPER mainly played a role in the early-growth phase of tumors, while CXCL10 and HOXA9 mainly played roles in tumor progression." (PMID 32432046, 2020). "Treatment with CEA-TCB triggered secretion of pro-inflammatory cytokines (IFNγ, TNFα, IL-2) and several chemotactic molecules (CXCL9, CXCL10, CXCL11, CXCL13) indicating the generation of a highly inflamed tumor microenvironment." (PMID 33330050, 2020). "In conclusion BMPER, CXCL10, and HOXA9 promote early tumor growth and progression by stimulating neovascularization of primary HGG." (PMID 32432046, 2020). "Supernatants derived from tumor tissues markedly facilitated CD8+ T cell migration, which was attenuated by anti-CXCL10 or anti-CXCR3 neutralizing antibodies." (PMID 32503584, 2020). "M1 macrophages can destroy tumor cells by producing inflammatory cytokines such as tumor necrosis factor (TNF)-α, IL-12, CXCL10 (IP10), CCL2 and nitric oxide (NO)." (PMID 32196489, 2020). "In this case, CXCR3+ tumor-specific T cells accumulate into tumors through interaction with CXCR3 ligands (CXCL9, CXCL10, and CXCL11)." (PMID 32292786, 2020). "Recent studies have shown that CXCL10 can enhance the antitumor activity of Th1 cells by inducing the recruitment of CXCR3 and CD8+ T cells to tumor sites and the production of Granzyme‐B induced by these cells." (PMID 32253815, 2020). "Overall, these data support a mechanism of hetIL-15 action in which lymphocyte trafficking to the tumor is controlled by a gradient of the chemokines CXCL9 and CXCL10." (PMID 32461349, 2020). "A study in colorectal cancer showed that chemokines CXCL9 and CXCL10 attract memory T lymphocytes and CX3CL1 recruits CTLs towards the tumour." (PMID 30232514, 2019). "This was indeed confirmed in the xenografts by IHC analysis, which stained tumor sections for CD8, CCL5, and CXCL10." (PMID 31221150, 2019).
tumor (continued). "We found ten potential prognostic genes, including eight tumor suppressor and/or driver genes (VEGFA, CCND1, BAX, IL7R, SHC1, FLT1, IL7, and JAK3), as well as two chemokines (CXCL9 and CXCL10)." (PMID 31661791, 2019). "Here we show that IL-17 signals to transformed epithelial (tumor) cells to suppress the expression of CXCL9 and CXCL10 chemokines." (PMID 31775909, 2019). "This study demonstrated a positive correlation of CXCL9, CXCL10, and CXCL11 mRNA expression with the density of tumor-infiltrating T and NK cells." (PMID 30873179, 2019). "Accordingly, we propose that GBE1 reduces the recruitment of CD8+ T cells into the tumor microenvironment by inactivating CCL5 and CXCL10, thus contributing to the immune escape in LUAD." (PMID 31221150, 2019). "Immunochemical analysis of primary tumor biopsies from patients demonstrated a relationship between higher type 1 IFN expression and higher intratumoral CXCL10 as well as increased numbers of CXCR3+ and granzyme B+ lymphocytes." (PMID 30899263, 2019). "Conversely, consistent with the angiostatic effects of CXCL9 and CXCL10 by binding to their receptor CXCR338, we earlier reported reduced angiogenesis in LLC tumors from Cav-2 KO mice as early as day 6 after tumor cell implantation." (PMID 31831780, 2019). "We also investigated the presence of CXCL12, CCL21, CXCL11, IP-10 (or CXCL10), CCL19, and CCL27, which participate to the recruitment of specific NK cell populations to the tumor site." (PMID 31105699, 2019). "Here we demonstrate that the tumor microenvironment in GBM patient cohort can be profiled by M1-like and M2-like microglia/ macrophage markers CXCL10 (M1-like) and CCL13 (M2-like) and by a subset of metalloprotease genes." (PMID 31142630, 2019). "Other research demonstrated that the use of DPP4, which inhibits CXCL9/CXCL10 processing intratumourally, increased cDC1 infiltration into B16F10 murine melanoma tumours." (PMID 31091774, 2019). "Since IFN-I is known to induce the expression of lymphocyte-recruiting chemokines such as CXCL9, CXCL10, and CXCL11, we measured the mRNA expression level of these chemokines in the tumor-containing lungs at 21 d.p.i." (PMID 31049360, 2019). "STING agonist upregulated the T cell chemokine CXCL10 with little effect on the DC attractant CCL20, suggesting that STING agonist therapy increases the adaptive anti-tumor T cell responses through multiple cellular mechanisms." (PMID 31036082, 2019). "The addition of IL-27 can promote CXCL10 production by MDSCs, resulting in the recruitment of anti-tumor NK and NKT cells reducing tumor size." (PMID 31681561, 2019). "It has been found that CXCR3-binding chemokines (such as CXCL9 and CXCL10) are critical and essential for the recruitment of activated CD8+ T cells to tumor sites." (PMID 31616443, 2019). "Tumor infiltrating cDC1s are also the main producers of different chemokines, including CXCL9 and CXCL10, which help to promote the recruitment of CD8+ T cells into the tumor microenvironment (TME)." (PMID 31736936, 2019). "For example, in a murine model for LGG, the introduction of mutant IDH1 or treatment with 2HG reduced protein levels of CXCL10 likely through decreased production of STAT123, and suppressed the accumulation of T cells at tumor sites." (PMID 31601888, 2019). "The mRNA induction in sorted CD14+ MΦ was manifold higher for CXCL10 and CCL2 as compared with tumor cells." (PMID 30850595, 2019). "In several of these therapeutic scenarios, intratumoral CD103+ DCs contributed to tumor immunity through production of T-cell recruiting chemokines such as CXCL9 and CXCL10." (PMID 31188899, 2019). "Several of the chemokines produced by the tumor cells, including CXCL9 and CXCL10, are important with respect to their capacity to attract T cells." (PMID 30192802, 2018). "Metastasis can be promoted by endothelial cell secretion of CXCL9 (and CXCL10), assisted by VEGF, within the tumor microenvironment or autocrine CXCL10/CXCR3 interactions on tumor cells." (PMID 30320116, 2018).
tumor (continued). "In vitro, the chemokines increased after radiotherapy in the parental tumor cell, and CCL2-5, CXCL9, CXCL10, CXCL16 were much higher than in the resistant cell." (PMID 30093664, 2018). "Concomitant with the release of ATP and CXCL10, increased migratory activity of THP-1 monocytes to tumor cell culture supernatants was observed qualitatively and quantitatively, and especially in combination treatment regimens." (PMID 30518936, 2018). "This cytokine reduces the production of CXCL10/IP-10 chemokine in infected microglial cells and thus reduces recruitment of lymphocytes that fight against CMV and tumor cells." (PMID 29467963, 2018). "In an immune stimulatory tumour microenvironment, eosinophils would produce high numbers of potent chemoattractants for CD8+T cells via STAT1, such as CCL5, CXCL10, CXCL1118." (PMID 29440650, 2018). "Efficient NK–DC interaction in the tumor can lead to increase of CXCR3 and CCR5 on DC, which can recruit CD8+ effector T cells to tumors, in the presence of chemokines CXCL9, CXCL10, and CCL5." (PMID 30200478, 2018). "When combined with BEV, GD2-CAR T cells infiltrated tumor mass, where they secreted IFN-γ which, in turn, induced release of CXCL10 by NB cells." (PMID 30510968, 2018). "Tumour-infiltrating lymphocytes were detectable throughout the E-MpM series and paralleled the coordinated expression of the CXCL9, CXCL10, and CCL5 chemokines acting in lymphocyte recruitment." (PMID 30510965, 2018). "Overall, in addition to attracting CARTs to tumor sites, the resulting enhanced secretion of IFN-γ and CXCL10 creates a pro-inflammatory TME favoring the development of antitumor immunity." (PMID 30386740, 2018). "IFNγ produced within the TME induces CXCL9, CXCL10, and CXCL11 expression, which correlates with tumor infiltrating CTL and Th1-effector cells and with a positive survival rate in colorectal cancer." (PMID 30319638, 2018). "IP-10/CXCL10 can recruit CXCR3+ T cells, including CD8+ T cells, which are important for the control of tumor growth, via the CXCR3 receptor expressed on activated T cells." (PMID 30228241, 2018). "In the early stages of MF, expression of CXCL9, CXCL10, and CXCR3 is believed to be important for recruitment and accumulation of tumor cells in the skin." (PMID 29915722, 2018). "As a member of the CXC chemokine family, CXCL10 binds to its receptor CXCR3 to exert biological functions in infectious diseases, immune dysfunction, chronic inflammation, tumor development and metastasis." (PMID 27765529, 2017). "Employing this approach, they recognized a core of nine cytokines that consistently correlated with efficacious tumour suppression: IL-12p70, IFN-γ, IL-1α, IL-1β, IL-2, IL-3, IL-6, CXCL10, and CXCL9." (PMID 29089667, 2017). "TAM derive from circulating monocytes, which are recruited into the substance of the tumor by a wide range of chemokines, especially MCP-1/CCL2, CXCL1, CXCL10 and SDF-1/CXCL12, released either by tumor cells or other stromal cells." (PMID 28098760, 2017). "Double-immunofluorescence staining showed chemokine expression (CXCL9, CXCL10 and GRO) in the tumour cell cytoplasm/nucleus and deposited in the extracellular matrix." (PMID 28386296, 2017). "As a last example of IFN-inducible CXCR3 interacting chemokines as potential tumor suppressors, CXCL9 and CXCL10 were found to promote the natural antitumor immunity of the host also in gastric cancer." (PMID 29379506, 2017). "High number of tumor infiltrating lymphocytes correlate with increased expression of a cluster of chemokines that comprise CCL2 and CXCL10, with CXCL9 and CXCL10 critically involved in the recruitment of effector CD8+ T cells." (PMID 29064427, 2017). "Nevertheless, the capacity to recruit immune cells such as regulatory T cells also implies that CXCL9, CXCL10, and CXCL11 can shape the microenvironment toward a rather tumor-promoting milieu." (PMID 29379506, 2017).